ERCC2 (ERCC excision repair 2, TFIIH core complex helicase subunit)
Diseases named in the same sentence as ERCC2 in open-access papers (continued):
Sharing a sentence is not in itself a finding about the gene and the disease.
Thrombocytopenia (3 papers, 2020 to 2024). A reduction in the number of circulating thrombocytes. "Safety analyses showed that the ERCC2 rs1799793 variant was significantly associated with the risk of grade ≥ 3 thrombocytopenia in the total cohort (multivariate: odds ratio 3.15, [95% CI 1.08–9.17]; p = 0.04)." (PMID 39339159, 2024). "In our study, significantly more patients with the ERCC2-rs13181 C allele had eye reactions and thrombocytopenia and needed dose reduction more often compared to patients with the A/A genotype." (PMID 32397974, 2020). "Specifically, the ERCC2-rs238406 CC genotype was associated with thrombocytopenia whereas the ERCC2-rs13181 C variant was correlated with thrombocytopenia as well as eye reactions." (PMID 32397974, 2020). "We also found that the ERCC2-rs238406 C/C genotype was associated with a higher frequency of thrombocytopenia." (PMID 32397974, 2020). "The ERCC2 rs1799793 variant could identify patients who are at risk of developing thrombocytopenia and would be candidates for preventive treatment with thrombopoietin receptor agonists." (PMID 39339159, 2024). "We found that ERCC1 was significantly associated with PFS and ERCC2 with thrombocytopenia." (PMID 39339159, 2024). "Furthermore, the ERCC2-rs238406 C/C genotype was associated with a higher frequency of thrombocytopenia (p = 0.03)." (PMID 32397974, 2020). "Also, eye reactions and thrombocytopenia were more common in patients with the ERCC2-rs13181 C allele compared to the A/A genotype (p = 0.006 and p = 0.004, respectively)." (PMID 32397974, 2020). "ERCC2- rs238406 C/C was also associated with a higher frequency of thrombocytopenia (p = 0.03)." (PMID 32397974, 2020). "Moreover, ERCC2 rs1799793 (p = 0.03 in a dominant model) and UGT1A1 rs3064744 (p = 0.03 in a recessive model) were significantly associated with thrombocytopenia." (PMID 39339159, 2024).
alopecia (2 papers, 2019). Hair loss usually from the scalp. "Univariate statistical analyses revealed that patients with ERCC2 rs13181 T/G and/or CYP3A4 rs2740574 A/G genotypes are more likely to develop alopecia; patients with ERCC2 rs238406 C/C genotype may develop leukopenia, and patients with GSTT1-null genotype could develop lymphocytopenia (III–IV)." (PMID 30914949, 2019).
diabetes (2 papers, 2020 to 2021). "Additionally, associations with CKD related pathologies, such as hypertension (GPX4, CYP11B2, ERCC4), cardiovascular disease, diabetes and cancer predisposition (ERCC2) were also observed." (PMID 31924810, 2020).
endometrial cancer (2 papers, 2012 to 2025). Primary or metastatic malignant neoplasm involving the endometrium (mucous membrane that lines the endometrial cavity). "We have also found that cancer history in first degree relatives increased endometrial cancer risk in the Gln/Gln variant of the p.Lys751Gln polymorphism of the ERCC2 gene." (PMID 22544315, 2012). "We found an association between the ERCC2 751Gln variant and endometrial cancer occurrence (OR 3.95; 95 % CI 1.88–8.31)." (PMID 22544315, 2012). "The 751 Lys/Gln polymorphism of the ERCC2 gene may be linked with endometrial cancer occurrence and its effect can be potentiated by variants of the XRCC1 gene or first degree relatives positive cancer history." (PMID 22544315, 2012). "Gene-gene interaction between the ERCC2 751Gln and XRCC1 194Trp variants also increased the risk of endometrial cancer (OR 4.41; 95 % CI 2.01–9.67)." (PMID 22544315, 2012).
endometriosis (2 papers, 2021 to 2025). The growth of functional endometrial tissue in anatomic sites outside the uterine body. "Certain variants in this gene have also been linked to the development of endometriosis, suggesting a potential role for ERCC2 in adenomyosis within the context of shared pathogenesis." (PMID 41374450, 2025).
Erythema (2 papers, 2024 to 2025). Redness of the skin, caused by hyperemia of the capillaries in the lower layers of the skin. "Polymorphisms in DNA repair genes (e.g., XRCC2, ERCC2, and ERCC1) and inflammatory mediators like IFNG were most linked to acute adverse effects, including erythema, desquamation, and oedema." (PMID 40507362, 2025).
Hypertension (2 papers, 2016 to 2020). The presence of chronic increased pressure in the systemic arterial system. "One of these (Ercc2) is annotated in RGD as being associated with hypertension." (PMID 26822062, 2016). "In addition, other genes were found to be associated with CKD related pathologies, such as hypertension (GPX4, CYP11B2, ERCC4), cancer predisposition (ERCC2), and cardiovascular disease (ERCC2)." (PMID 31924810, 2020).
liver cirrhosis (2 papers, 2020 to 2022). "The obtained results have demonstrated that SNPs within XRCC1, ERCC2 genes may confer susceptibility to liver cirrhosis in chronic hepatitis B patients." (PMID 33171788, 2020). "In conclusion, this study shows that functional and potentially functional SNPs within XRCC1 and ERCC2 genes may confer susceptibility to HBV-associated liver cirrhosis." (PMID 33171788, 2020). "Three genetic variations (ERCC2: rs238406, XRCC1: rs25487, NBN: rs2735383) had diverse frequency in CHB patients with liver cirrhosis and with no fibrosis, highlighting their possible role in HBV-induced liver disease progression." (PMID 33171788, 2020). "Moreover, for rs238406 (ERCC2), rs25487 (XRCC1), and rs2735383 (NBN), we also found significant differences in genotypic distribution between the liver cirrhosis and no fibrosis group." (PMID 33171788, 2020).
Lynch syndrome (2 papers, 2018 to 2019). An autosomal dominant hereditary neoplastic syndrome characterized by the development of colorectal carcinoma and a high risk of developing endometrial carcinoma, gastric carcinoma, ovarian carcinoma, renal pelvis carcinoma, and small intestinal carcinoma. "Our findings revealed that polymorphisms of DNA repair genes that include NUDT1,ERCC2, and MUTYH are associated with CRC in patients with Lynch syndrome in Chinese population." (PMID 29664240, 2018). "Our results demonstrated that patients with Lynch syndrome harboring at least one risky genotype in MUTYH, NUDT1, and ERCC2 SNPs were at an increased risk of CRC compared to those without risky genotype." (PMID 29664240, 2018).
oral cancer (2 papers, 2013 to 2024). "We performed a meta-analysis to systematically summarize the possible association of ERCC2 rs1799793 and rs13181 polymorphisms with oral cancer risks." (PMID 24330540, 2013). "Among three studies of ERCC2 rs1799793 polymorphisms, one study included the association between this polymorphism with oral cancer risk and all of the three studies contain the association between the polymorphism and oral leukoplakia risk." (PMID 24330540, 2013). "To date, there are studies reporting the association between polymorphisms of ERCC2 codon 312 and 751with oral cancer risk but these published data were contradictory." (PMID 24330540, 2013). "The findings from this meta-analysis suggested that there was a significant association between rs13181 polymorphism in ERCC2 gene and risk of oral cancer, which provided new evidence for the susceptibility and etiology of oral cancer." (PMID 24330540, 2013). "So we perform an updated meta-analysis on all available case–control studies to assess the oral cancer risk with rs13181 and rs1799793 in ERCC2 gene." (PMID 24330540, 2013). "The current study is the first meta-analysis of the association between ERCC2 rs1799793 and rs13181 polymorphisms with the risk of oral cancer." (PMID 24330540, 2013). "Single nucleotide polymorphisms (SNPs) of ERCC2 gene are suspected to influence the risks of oral cancer." (PMID 24330540, 2013). "Therefore, more studies are needed to provide more evidence on the association between ERCC2 polymorphisms and oral cancer risks in Caucasians and other ethnic populations." (PMID 24330540, 2013). "Until now, there was no meta-analysis or systematic review on the risk of oral cancer with ERCC2 polymorphism." (PMID 24330540, 2013). "Third, in stratified analysis we only studied the association between ERCC2 rs13181 polymorphism and oral cancer in Asians but could not evaluate the association in Caucasians because of the limited studies from Caucasian population." (PMID 24330540, 2013).
rectal cancer (2 papers, 2013 to 2018). A primary or metastatic malignant neoplasm that affects the rectum. "For rectal cancer, ERCC2 expression correlated with favourable T stage; XPA expression predicted worse TNM stage." (PMID 29568775, 2018). "Subjects with high ERCC2 expression were less likely to be observed in T3/T4 stage than low ERCC2 expression individuals in rectal cancer." (PMID 29568775, 2018). "For rectal cancer, significant relation was observed between ERCC2 high expression and favourable T stage (P = 0.019); high XPA expression obviously predicted worse TNM stage (P = 0.025), T stage (P = 0.019), and N stage (P = 0.008)." (PMID 29568775, 2018).
UV-sensitive syndrome (2 papers, 2016 to 2021). UV-sensitive syndrome is a condition that is characterized by sensitivity to the ultraviolet (UV) rays in sunlight. "Interestingly, our results also found ERCC2(XPD), ERCC3(XPB) or ERCC5(XPG) mutations in two cases of UV-sensitive syndrome and in two cases with mixed XP/CS phenotypes." (PMID 27004399, 2016).
Xeroderma pigmentosum complementation group A (2 papers, 2023 to 2025). Xeroderma pigmentosum complementation group A (XPA) is a severe form of xeroderma pigmentosum (XP; see this term), a rare photodermatosis predisposing to skin cancers. "Such proteins are tDNA damage-binding protein 1 (DDB1), ERCC2, Xeroderma pigmentosum complementation group A (XPA), and xeroderma pigmentosum complementation group C (XPC)." (PMID 37206523, 2023).
Anxiety (1 paper, 2021). Intense feelings of nervousness, tension, or panic often arise in response to interpersonal stresses. "After adjustment for environmental factors, SNPs and haplotypes of ERCC1 and ERCC2 were associated with different domains of QoL, depression and anxiety in LC patients." (PMID 34284736, 2021). "SNPs and haplotypes of ERCC1 and ERCC2 were associated with different domains of QoL, depression and anxiety in LC patients." (PMID 34284736, 2021). "ERCC2 rs13181-rs3916874-rs238416 haplotype was associated with emotional function, pain in other parts, chest pain, dysphagia and anxiety." (PMID 34284736, 2021). "This study showed that ERCC1 rs3212986, ERCC1 rs3212986-rs11615, ERCC2 rs13181-rs3916874-rs238416 were associated with anxiety or depression in LC patients." (PMID 34284736, 2021). "ERCC2 rs13181-rs3916874-rs238416 haplotype was associated with emotional functioning (P = 0.035), pain at other sites (OR 1.88, P = 0.014), chest pain (OR 0.42, P = 0.02), dysphagia (OR 2.82, P = 0.048), and anxiety status (OR 0.23, P = 0.009)." (PMID 34284736, 2021). "The current study is intended to examine the effect of SNPs and haplotypes of ERCC1 and ERCC2 on the QoL, depression and anxiety of LC patients with demographic and clinical characteristics correction." (PMID 34284736, 2021). "The current study is intended to explore the relationship between SNPs and haplotypes of ERCC1 and ERCC2 and the QoL, depression and anxiety status of patients with LC." (PMID 34284736, 2021).
autism (1 paper, 2025). Persistent deficits in social interaction and communication and interaction as well as a markedly restricted repertoire of activity and interest as well as repetitive patterns of behavior. "Two heterozygous pathogenic variants in the ERCC2 gene were identified through Autism/ID Gene Panel." (PMID 39976384, 2025). "Autism/ID gene Panel identified a compound heterozygous variant in ERCC2 gene causing TTD." (PMID 39976384, 2025).
axial osteosclerosis (1 paper, 2025). "Extremely rare osteosclerotic disorders also include Caffey disease, Lenz-Majewski hyperostotic dwarfism, trichothiodystrophy-1 with axial osteosclerosis, and melorheostosis which are caused by mutations in COL1A1, PTDSS1, ERCC2, and MAP2K1, respectively." (PMID 40198394, 2025).
B cell deficiency (1 paper, 2024). A broad classification of disorders where circulating numbers of B lymphocytes are decreased or ineffective.
Cirrhosis (1 paper, 2020). A chronic disorder of the liver in which liver tissue becomes scarred and is partially replaced by regenerative nodules and fibrotic tissue resulting in loss of liver function. "We showed that SNPs within XRCC1 and ERCC2 genes are independently associated with increased risk of cirrhosis." (PMID 33171788, 2020). "As compared to the no fibrosis group, the cirrhotic group harbored a higher frequency of ERCC2 rs238406 G allele, which appeared to be a risk factor for cirrhosis, and lower numbers of the variant XRCC1 rs25487 C allele, which had a protective effect." (PMID 33171788, 2020). "The homozygous TT genotype at ERCC2 rs238406, CC at XRCC1 rs25487, and GG at NBN rs2735383 were significantly associated with a lower risk of cirrhosis." (PMID 33171788, 2020). "After adjusting for sex and age, logistic regression analysis showed that CHB individuals carrying the rs238406 G allele (ERCC2) and rs25487 T allele (XRCC1) are at increased risk of developing cirrhosis and liver failure." (PMID 33171788, 2020).
colon adenoma (1 paper, 2018). An adenoma that arises from the colon. "On the basis of Sabates-Bellver Colon dataset, overexpression of ERCC2 was detected in both colon adenoma and rectal adenoma, with fold change of 2.391 and 2.813, respectively." (PMID 29568775, 2018).
colorectal tumor (1 paper, 2021). "However, a total of 99% concordance rate for SNP in ERCC2 genotyping from FFPE colorectal tumor material and peripheral blood was found in the study of Van Huis-Tanja." (PMID 32546699, 2021).
epithelioid sarcoma (1 paper, 2025). An aggressive malignant neoplasm of uncertain differentiation, characterized by the presence of epithelioid cells forming nodular patterns. "Distinct patterns of DDR gene alteration frequencies were observed across histologic subtypes, with >20 subtypes identified with individual DDR genes altered in ≥3% of samples, including 3.0% of epithelioid sarcoma and 6.5% of perivascular epithelioid cell tumor samples harboring ERCC2 mutations." (PMID 40563612, 2025).
esophageal adenocarcinoma (1 paper, 2022). A malignant tumor with glandular differentiation arising predominantly from Barrett mucosa in the lower third of the esophagus. "Additionally, variant alleles in NER SNPs ERCC2 Lys751Gln, ERCC1 8092 C/A and ERCC1 118C/T were individually associated with esophageal adenocarcinoma risk." (PMID 35955506, 2022).
gynecological cancer (1 paper, 2025). "Further research is needed to elucidate the relationship between ERCC2 Lys751Gln polymorphism and tumor susceptibility, especially concerning gynecological cancers." (PMID 40777111, 2025).
hypogammaglobulinemia (1 paper, 2024). "This indicates that ERCC2 deficiency is associated with impaired adaptive immunity, in particular antibody deficiency." (PMID 39055713, 2024). "In summary, our analyses confirmed the pathogenicity of novel ERCC2 mutations and show that ERCC2 deficiency is associated with antibody deficiency most likely due to altered B-cell differentiation resulting from impaired BCR-mediated B-cell activation and activation-induced gene transcription." (PMID 39055713, 2024). "In this context our study shows that ERCC2 might be a likely candidate to be included in the list of NER-associated gene mutations causing antibody deficiency." (PMID 39055713, 2024). "Our results should encourage the immunological investigation of patients harboring ERCC2 mutations, as well as mutation analysis of ERCC2 in patients with primary antibody deficiency with unknown molecular mechanism." (PMID 39055713, 2024). "Impaired BCR mediated B-cell activation likely contributes to the antibody deficiency in TTD1 deficient patients, however it is not excluded that the previously reported defects in inborn immunity and T-cell functions might also contribute to impaired antibody production in ERCC2 deficiency." (PMID 39055713, 2024).
Immunodeficiency (1 paper, 2024). Failure of the immune system to protect the body adequately from infection, due to the absence or insufficiency of some component process or substance. "The clinical presentation of the patient (TTD, XP and immunodeficiency), the fact that her LCL cells’ UV sensitivity was defective to an extent comparable to that of cells from patients 1 and 2 strongly argue in favor of defective NER associated with ERCC2 deficiency." (PMID 39055713, 2024).
infiltrating ductal carcinoma (1 paper, 2021). "The (c.2164C>T; p.(Arg722Trp)) variant in the ERCC2 gene was found in a patient (III-1) with monolateral infiltrating ductal carcinoma diagnosed at 84 years." (PMID 34026625, 2021).
juvenile idiopathic arthritis (1 paper, 2011). Juvenile idiopathic arthritis (JIA) is the term used to describe a group of inflammatory articular disorders of unknown cause that begin before the age of 16 and last over 6 weeks. "Slight downregulation of ERCC2 expression was also observed in systemic juvenile idiopathic arthritis." (PMID 21496236, 2011).
laryngeal squamous cell carcinoma (1 paper, 2019). A squamous cell carcinoma that arises from the larynx. "Analysis of laryngeal squamous cell carcinoma showed an association with lower susceptibility risk in ERCC1 rs11615 and ERCC2 rs13181 SNPs." (PMID 30959967, 2019).
leukodystrophy (1 paper, 2025). Leukodystrophies are a group of rare, progressive, metabolic, genetic diseases that affect the brain, spinal cord and often the peripheral nerves. "The identification of hypomyelination in TTD due to ERCC2 sheds a light on the molecular diagnosis and contributing to the limited literature on ERCC2 variants and associated hypomyelinating leukodystrophy in patients with TTD." (PMID 39976384, 2025). "The findings highlight a rare association between ERCC2 mutations and hypomyelinating leukodystrophy, expanding the current understanding of TTD‐related neurodevelopmental disorders." (PMID 39976384, 2025).
leukoplakia (1 paper, 2013). A white patch or plaque on a mucous membrane that cannot be characterized clinically or pathologically as any other disease. "This meta-analysis suggested that rs13181 (ERCC2 Lys751Gln) might be associated with oral leukoplakia risk." (PMID 24330540, 2013).
liver fibrosis (1 paper, 2020). "Moreover, ERCC2 rs238406, acting as a biomarker of high liver fibrosis stage, suggests an important role of the functional ERCC2 SNPs in the etiology of HBV-induced liver damage in a Caucasian population." (PMID 33171788, 2020).
lymph node metastasis (1 paper, 2008). "However, the unfavorable genotype ERCC2 2251A>C (P = 0.006), tumor invasion depth (P = 0.025), lymph node metastasis (P = 0.011) and cancer stage (P = 0.008) were significantly correlated with early relapse." (PMID 18267032, 2008).
Oral leukoplakia (1 paper, 2013). A thickened white patch on the oral mucosa that cannot be rubbed off. "In conclusion, our meta-analysis supported that the rs13181 polymorphism in ERCC2 gene more likely contribute to the increasing risk of oral leukoplakia." (PMID 24330540, 2013). "Rs13181 in ERCC2 gene might be associated with oral leukoplakia risk." (PMID 24330540, 2013).